EZR (ezrin)
Diseases named in the same sentence as EZR in open-access papers (continued):
Sharing a sentence is not in itself a finding about the gene and the disease.
tumor (continued). "Podoplanin has been reported to enhance tumour invasion by enhancing cell motility through interaction with actin in the cytoskeleton via proteins such as ezrin, radixin, and moesin." (PMID 31452946, 2019). "Moesin is a member of the ERM (ezrin, radixin and moesin) proteins that participate in cell migration and tumor invasion through transductional signals sent to actin filaments by glycoproteins, such as podoplanin." (PMID 29310601, 2018). "OSA tumors, which contained lower mtDNA copies, have higher Ezrin mRNA compared to matched non-tumor control tissues which further suggests the correlation between mtDNA content and tumorigenesis." (PMID 30576337, 2018). "This binding event promotes ezrin and F-actin interaction through ezrin activation, leading to enhanced transendothelial migration of tumor cells." (PMID 28493957, 2017). "Ezrin is regarded as one of the promising key components in tumor metastasis, since it plays a role in interaction between the cell and its microenvironment, which facilitates intracellular signal transduction." (PMID 28298808, 2017). "Zhang demonstrated that ezrin ectopic overexpression in the MG63 OS cell line resulted in increased tumor migration and cell invasion in vitro." (PMID 28061797, 2017). "Over half (68%) of the tumor cells that were positive for ezrin expression demonstrated cytoplasmic immunoreactivity." (PMID 28246524, 2017). "It is reported in previous study that dynamic regulation of Ezrin phosphorylation at amino acid T567 that controls structural transitions of this protein plays a pivotal role in tumor progression and metastasis." (PMID 28423676, 2017). "Ezrin has been shown to play a role in tumor growth and metastasis through several mechanisms including drug efflux, prevention of apoptosis, aberrant signal transduction, and phagocytosis in certain cancers." (PMID 28246524, 2017). "Ectopic overexpression of ezrin in the OS cell line MG63 promoted tumor cell invasion and migration." (PMID 28061797, 2017). "In contrast, the 5-year EFS for patients whose tumor showed high ezrin intensity was 78% (95% CI: 57%–93%) compared to 55% (95% CI: 35%−74%) for those with low ezrin intensity (P = 0.03)." (PMID 28246524, 2017). "Similar to a prior report where high level ezrin expression was detected in 80% of EWS tumor samples, ezrin was expressed in 72% of the tumors in our study." (PMID 28246524, 2017). "Considering the importance of Ezrin in tumor growth, we focused on the relationship between Ezrin and different gastrointestinal cancers." (PMID 29190988, 2017). "Ezrin was discovered to be integral in OS and metastasis due to its ability to drive tumor progression by allowing OS metastatic cells to overcome a variety of stresses." (PMID 28061797, 2017). "Ezrin primarily acts as a linker between the plasma membrane and the cytoskeleton and is a key component in tumor metastasis." (PMID 26943769, 2016). "Ezrin-mediated effects on Akt and ERK1/2 activity have been linked to its ability to promote tumor progression and metastasis." (PMID 26933912, 2016). "In vitro, podocalyxin overexpression induced a collective migration of MCF-7 tumor cells in two-dimensional (2-D) monolayer culture that was dependent on the activity of the actin scaffolding protein ezrin, a cytoplasmic binding partner of podocalyxin." (PMID 26796961, 2016). "Although the roles of Ezrin in tumor cell migration and invasion abilities are well understood, other Ezrin-mediated tumor cell activities remain to be elucidated, including its role in EMT." (PMID 26933912, 2016). "Our data and studies of other investigators suggest impaired ability of cells with reduced ezrin expression in processes that include remodeling of their surrounding extracellular matrix, which is a crucial step in tumor dissemination." (PMID 27622508, 2016).
tumor (continued). "The 4.1 proteins family is characterized by FERM (Four-point-one, Ezrin, Radixin, Moesin) domains, many of which have related functions in influencing the biologic characteristics of tumor cells, as reported mainly with regard to cancer progression." (PMID 27487132, 2016). "For example the combination of anti-Ezrin and anti-ENOA1.2 with the tumor associated marker CA19.9 lead to a sensitivity of 100%." (PMID 26840568, 2016). "shRNA silencing in OC cell lines showed the involvement of ezrin more than p130Cas in processes that include ECM remodeling which is essential for tumor dissemination." (PMID 27622508, 2016). "There is an increased Ezrin phosphorylation at threonine 567 in liver metastasis compared to the primary tumor." (PMID 26202611, 2015). "Research on ezrin, CD44, and VEGF and their correlation with tumor prognosis will help to further reveal the underlying mechanism of the invasion and metastasis of GCTB and prognosis of GCTB patients." (PMID 25929323, 2015). "In cancer cells however, Ezrin seems to act differently as it plays a critical role during tumor progression by positively regulating the cell cycle progression." (PMID 26202611, 2015). "Ezrin is abnormally expressed in many tumor tissues and affects cellular motility, proliferation, apoptosis, and cycle and plays an important role in invasion and metastasis of tumors." (PMID 25929323, 2015). "Indeed, combined low miR-223 with high target mRNA ECT2 expression in osteosarcoma was significantly associated with tumour grade, chemo-resistance, development of metastases and tumour recurrence, as was in that same cohort, the combined low miR-183 with high target mRNA EZRIN expression." (PMID 26204834, 2015). "As a novel feature, the present paper also entails a longitudinal study of ezrin expression, e.g. comparison of expression in primary and recurrent tumours, the majority being local recurrences, in a small subset of cases." (PMID 25278252, 2014). "In contrast, in adjacent non-tumor tissues, the percentages of cells with strongly positive ezrin, ezrinThr-567 and ezrinTyr-353 expression were 3.3%, 4.7% and 1.3%, respectively, and completely negative in normal lung tissue counterparts." (PMID 24629131, 2014). "Immunohistochemical expression of cytoplasmic and membranous ezrin was evaluated in tissue microarrays with primary tumours from 272 cases and recurrent tumours from 28 cases." (PMID 25278252, 2014). "Ezrin, a cytoplasmic peripheral membrane protein, has been shown to interact with E-cadherin to participate in the metastasis of tumor cells." (PMID 24959233, 2014). "Ezrin interacts with several cell signaling molecules involved in tumour progression including hepatocyte growth factor (HGF) receptor Met, β4-integrin, and Src family kinases." (PMID 25231728, 2014). "An intriguing novel finding of our present analysis is the inverse correlation of KLK5 and ezrin, a membrane cytoskeleton linker protein, which has been shown to increase tumor motility and invasion, and is considered key to the metastatic process." (PMID 25593998, 2014). "Next, we examined the role of Src/ezrin in tumour-induced migration and tube formation of primary hLEC in vitro." (PMID 25231728, 2014). "Ezrin KD in the presence of endogenous Src expression in MDA231 cells also significantly inhibited tumour-induced vascularization." (PMID 25231728, 2014). "Ezrin has active role in regulating tumor growth and progression and metastatic dissemination of many cancers." (PMID 25580109, 2014). "Podocalyxin has been shown to increase metastatic potential of tumour cells, in vitro, through its interaction with ezrin." (PMID 25531390, 2014). "Here we also found that ezrin was significantly upregulated in NSCLC compared with the adjacent non-tumor tissues and normal lung tissue counterparts (P < 0.01)." (PMID 24629131, 2014).
tumor (continued). "The percentages of positive ezrin, ezrinThr-567 and ezrinTyr-353 cells in adjacent non-tumor tissues were 31.3%, 14.0% and 11.3%, respectively, and 35.7%, 14.3% and 7.1% in normal lung tissue counterparts, respectively." (PMID 24629131, 2014). "IHC staining was initially used to validate Src and ezrin antibodies and to assess their localization in normal and tumour breast tissue." (PMID 25231728, 2014). "It will also be relevant to examine the effects of neoadjuvant chemotherapy on ezrin expression in tumours from cystectomy specimens, to determine their suitability for prognostication purposes." (PMID 25278252, 2014). "qRT-PCR data confirmed increased levels of ezrin mRNA expression in NSCLC samples compared with adjacent non-tumor tissues and normal tissue counterparts in fresh tissues." (PMID 24629131, 2014). "We further show that ezrin tyrosine 477, a Src phosphorylation site, plays a regulatory role in tumour-induced angio/lymphangiogenesis." (PMID 25231728, 2014). "The present study provides novel insights into the regulatory role of ezrin and Src in tumour-induced angio/lymphangiogenesis, a precondition for early tumour cell dissemination." (PMID 25231728, 2014). "Despite the growing evidence pointing to ezrin as a key promoter of tumour metastasis, the molecular basis of ezrin function remains poorly understood." (PMID 25231728, 2014). "Altogether, these studies demonstrate that not only the expression level of ezrin but also its phosphorylation status and subcellular localization should be considered to better understand its role in tumor progression." (PMID 24086451, 2013). "To date, a number of genes have been identified that modulate lymphatic tumor metastasis when they are highly expressed in certain tumor cells, such as Ezrin, AF1QN, MMP-11, or Annexin A7." (PMID 24188284, 2013). "We also observed that the nuclear localisation of ezrin was strongly correlated with grade 3 BC tumours, thus confirming the potential role of nuclear ezrin immunodistribution in carcinogenesis." (PMID 23420497, 2013). "Currently, increased evidence suggests that a membrane-cytoskeleton linker, ezrin, plays a pivotal role in tumor invasion and metastasis." (PMID 24182314, 2013). "Overall p-ezrin protein expression significantly increased with increasing age, tumor cytohistological de-differentiation (Grade), proliferation (Ki-67) and with a poorer prognosis as indicated by an increasing Nottingham Prognostic Index (NPI)." (PMID 24086451, 2013). "Ezrin participates in regulating cell-cell and cell extracellular matrix adhesion, thus influencing tumor cell invasion and other biological behavior." (PMID 24182314, 2013). "Evidence from both animal models and prospective human studies show correlations between ezrin expression levels and tumor progression, consistent with a crucial role for ezrin in tumor dissemination." (PMID 23894313, 2013). "Correlation analysis further revealed that tumor p-ezrin protein expression levels were positively correlated with increasing levels of the proto-oncogene receptor HER2/ErbB2." (PMID 24086451, 2013). "Overall, our findings demonstrate for the first time that km23-1 regulates not only CRC cell migration, invasion, and tumor growth, but also critical markers of a pro-invasive phenotype, including TGFβ1, Ezrin, and ERK." (PMID 23755307, 2013). "Third, although immunohistochemistry was the most commonly applied method for detecting Ezrin in situ, RT-PCR method had also been used for the evaluation of the levels of Ezrin gene or mRNA expression in tumor tissue." (PMID 23894313, 2013). "A correlation between ezrin overexpression and aggressive cancer behavior has been recently reported in various tumor types." (PMID 23357878, 2013). "Recently, increasing reports also showed that the critical functions of Ezrin are the regulation of cell shape, motility, adhesion and signal transduction, all of which are important for tumor development and progression." (PMID 23039327, 2012).
tumor (continued). "Since tumor cell invasion is affected by the 3D matrix milieu, we decided to further characterize the Y477F ezrin phenotype in a 3D Matrigel embedded culture system." (PMID 22397367, 2012). "Our finding that Y477F ezrin attenuates the invasive tumor phenotype in 3D Matrigel cultures in vitro prompted us to assess the effect of Y477F ezrin on in vivo tumor progression using our highly metastatic AC2M2 carcinoma cell line model." (PMID 22397367, 2012). "While Y477F ezrin was found to have a marked attenuating effect on local invasion during early phases of tumor growth, a reduction in the proportion of mice with distant metastasis was also observed, though this effect failed to reach significance." (PMID 22397367, 2012). "A VSVG-tagged 80 kDa protein was detected by western blotting on protein extracts from Y477F ezrin expressing tumors, indicating the presence of the mutant ezrin form in the tumor tissues." (PMID 22397367, 2012). "It would be thus important to address the role of ezrin/WWP1 interaction in the regulation of Met activity in tumor cells and in metastasis as Met plays a central role in these processes." (PMID 22629406, 2012). "Tumour markers like ezrin, HSP90, CD83, and others also reveal a potential as biomarkers of BCG treatment response." (PMID 22919375, 2012). "AC2M2 cell clones expressing control vector or Y477F ezrin were engrafted into the mammary gland of recipient mice and primary tumor growth was monitored every 2-3 days." (PMID 22397367, 2012). "A similar role of the RhoA/ROCK cascade has been established in fibroblast and in other tumor cells, where it mediates ezrin activation or redistribution." (PMID 21818323, 2011). "Ezrin, whose expression correlates with progression in many tumor types, is involved in multiple metastatic pathways." (PMID 20856924, 2010). "Ezrin plays important roles in cell motility, invasion and tumor progression, and it is especially crucial for metastasis." (PMID 20569470, 2010). "The NEP N-terminus also affects tumor formation by competing with the hyaluronan receptor CD44 for Ezrin/Radixin/Moesin (ERM) binding thereby reducing the invasive capacity of cancer cells." (PMID 20957047, 2010). "Taken together, the observed effects of ezrin overexpression and silencing on the cell malignant transformation indicate a role for ezrin in regulating tumor metastasis and progression." (PMID 20569470, 2010). "It has been recently reported that phosphorylation of ezrin is required for metastatic behavior of tumor cells." (PMID 20569470, 2010). "We have demonstrated the risk of epigenetic drug treatment on otherwise poorly metastatic tumor cells in which potent pro-metastatic genes such as Ezrin can be epigenetically upregulated." (PMID 20856924, 2010). "Among the 104 HBV HCC patients undergoing hepatectomy, 27 (29.6%) had variable positive ezrin immunoreactivity in the cytoplasm of the tumor cell." (PMID 19604375, 2009). "Multivariate forward logistic regression analysis showed that small tumor size, cirrhotic liver, poor differentiation, and vascular invasion are the four independent factors associated with HBV HCC patients with positive ezrin immunoreactivity." (PMID 19604375, 2009). "HBV HCC patients with ezrin over-expression independently have smaller tumor size, cirrhotic liver background, poor tumor differentiation, and more vascular invasion." (PMID 19604375, 2009). "Our data strengthen the role of ezrin in OS and the need to further explore the targeting of ezrin in this neoplasia." (PMID 20003259, 2009). "A compelling parallel is provided by recent studies linking Ezrin over-expression to tumour metastasis – a fundamental property of which is junctional instability." (PMID 17971776, 2008). "To examine the correlation of Pyk2 with other potential metastatic genes, we detected the mRNA levels of ezrin and fibronectin in the liver tumour and non-tumour tissues." (PMID 17551499, 2007).
tumor (continued). "The membrane cytoskeletal crosslinker ezrin participates in several functions including cell adhesion, motility and cell survival, and there is increasing evidence that it regulates tumour progression." (PMID 15987432, 2005). "EZR, a membrane-actin linker protein, plays a critical role in cell signaling and tumor survival." (PMID 40982350, 2025). "Moreover, the cell surface adhesion molecule CD44 complexes with Ezrin to enhance tumor cell adhesion and invasion when co-localized in PCa-endothelial cells, facilitating tumor progression." (PMID 39055653, 2024). "The present findings corroborate these previous studies, indicating that the high expression of EZR may contribute to the malignant phenotype of these neoplasms." (PMID 38972247, 2024). "While it is unclear whether this process contributes to the malignant phenotype of a tumor, the hyperphosphorylation of Ezrin relating to tumor metastasis implicates the importance of Ezrin in tumorigenesis." (PMID 37371090, 2023). "Lastly, Ezrin also promotes the survival of tumor cells at distant organs following extravasation." (PMID 37371090, 2023). "However, Ezrin dysfunction has been correlated with the progression of many diseases, including cancer and tumor metastasis." (PMID 37371090, 2023). "Notably, Ezrin has been reported to interact with immune cells, allowing tumor cells to escape immune attack in metastasis." (PMID 37371090, 2023). "Also, the western blot examination revealed that the cancer tissue had the highest expression level of ezrin protein, and this level gradually decreased as we moved far from the tumor." (PMID 37061568, 2023). "Overall, the available evidence suggests that regulation of Ezrin gene transcription may exhibit similar characteristics in different types of tumor cells, and that Ezrin has potential as a valuable prognostic biomarker and biotherapeutic target in tumors." (PMID 37791063, 2023). "Furthermore, Ezrin’s interactions with the immune system allow it to aid tumor cells in evading immune surveillance." (PMID 37371090, 2023). "Also, cancerous tissue had the highest expression level of ezrin protein, and this level gradually decreased as we moved away from the tumor." (PMID 37061568, 2023). "Based on the results presented herein, we propose that the inhibition of ezrin could be further tested and explored as a novel strategy to counteract resistance to the BRAFV600E inhibitors in tumours harbouring the BRAFV600E mutation." (PMID 37629086, 2023). "Abnormal expression of Ezrin protein can confer high metastatic activity on tumor cells, affect and participate in multiple processes involved in tumor metastasis, and may even be a factor determining tumor metastasis." (PMID 37791063, 2023). "CD44, also being overexpressed in the resistant cells, is a cell-adhesion molecule known to interact with ezrin to form a complex that plays important roles in regulating tumour–endothelium interactions, cell migration, cell adhesion, tumour progression and metastasis." (PMID 37629086, 2023). "Additionally, we also found a significant inverse correlation between CD34 positive capillaries and Ezrin expression in tumor tissue." (PMID 36142656, 2022). "In addition, there was a positive correlation between Breslow tumor thickness and Ezrin positive cells (Tb = 0.260, p = 0.018)." (PMID 36142656, 2022). "Overexpression of Ezrin is seen as a tumor prognosis marker of several human cancers." (PMID 35311087, 2022). "While we focused on targeting microscopic metastasis, it would be important for future studies to assess whether anti-ezrin treatment can target dormant tumor cells as well." (PMID 36923551, 2022). "In addition, AKT inhibitors (MK2206) or PI3K inhibitors (LY294002) can block ezrin-mediated tumor growth and metastasis by inhibiting the PI3K/AKT signaling pathway." (PMID 36355541, 2022). "Furthermore, the elevated ezrin expression in circulating tumor cells (CTCs) correlates with distant metastases." (PMID 36077137, 2022).